ENSG00000100101 (novel transcript)
Gene: Protein-coding gene on chromosome 22 (37,686,414 to 37,726,503, forward strand). Ensembl gene ENSG00000100101.
Genetic constraint (gnomAD): Missense variants: 274 observed, 272.44 expected, observed/expected ratio (o/e) 1.01, 90% interval 0.91 to 1.11. Synonymous variants: 128 observed, 110.26 expected, observed/expected ratio (o/e) 1.16, 90% interval 1 to 1.34.